MUC16 (mucin 16, cell surface associated)
Diseases named in the same sentence as MUC16 in open-access papers (continued):
Sharing a sentence is not in itself a finding about the gene and the disease.
tumor (continued). "Binding of the tumor cells to the mesothelium via the mesothelin-MUC16 interaction may provide a necessary first step for metastasis." (PMID 17067392, 2006). "Blocking the binding of MSLN and MUC16 may be a promising approach to inhibiting tumor metastasis." (PMID 41400642, 2025). "Another factor relating to better therapy response in HPV(+) tumors could be that HPV(−) exosomes are enriched in tumor-promoting and immunosuppressive proteins such as MUC-1, HLA-DRA, MUC-4, and MUC-16, which give protection to tumor cells against NK cell-mediated lysis." (PMID 41154440, 2025). "Finally, we assessed the diagnostic performance of TFF2 alongside conventional tumor markers, including CEA (CEACAM5) and CA125 (MUC16), for PanIN and PC through ROC curve analysis, and the AUC values were 1.000 and 0.904, significantly outperforming other tumor markers." (PMID 41040532, 2025). "Therefore, MUC16 mutations may assist in HCC prognosis and should be further studied in this tumour type." (PMID 38825709, 2024). "We hypothesize that specific antibodies targeting MUC16 and CD16 can increase the distance between MUC16 and the MUC16 receptor on NK cells by recognizing the MUC16 antibody on tumor cells and the CD16 antibody on NK cells respectively, so that the NK cells can function normally." (PMID 38758220, 2024). "In addition, MUC16 also helps tumor immune escape by inhibiting T cells and NK cells." (PMID 38758220, 2024). "The current review offers an exhaustive exploration of the roles of MUC1 and MUC16 in the context of cancer biomarkers, elucidating their critical contributions to the mechanisms of cellular signal transduction, regulation of immune responses, and the modulation of the tumor microenvironment." (PMID 38361923, 2024). "However, MUC16 mutations promote good prognosis and anti-tumor immune response in patients with or without high mutation load." (PMID 38758220, 2024). "In addition, this will be exceptionally useful in investigating the anti-tumor potential of anti-MUC16 mAb in the context of complex tumor microenvironments and strategizing combinations with checkpoint blockade molecules in pursuit of discovering novel immunotherapeutic regimens." (PMID 37567918, 2023). "Initially, we could not determine whether MUC16 mutation was also associated with the prognosis and tumor immunity in Chinese patients and whether it could lead to the same immune response due to the lack of clinical data in the ICGC database." (PMID 37932988, 2023). "However, rather than simply a passive marker reflecting tumor burden, MUC16 may have a more active role by binding to immune cells and altering their tumor response." (PMID 35219339, 2022). "For example, MUC16 could hinder the targeting of NK cells to tumor cells." (PMID 35568842, 2022). "While this could simply reflect greater or increasing tumor burden, observations suggest that MUC16 has a more active role in disease progression by binding to cell surfaces of peripheral blood mononuclear cells (PBMCs) including NK cells and blunting their tumoricidal ability." (PMID 35219339, 2022). "However, it still remains elusive whether MUC16 detection in tumor tissue and serum levels of CCA patients correlate or have similar prognostic value." (PMID 36230626, 2022). "Thus, alterations in MUC16 enhance the tumor invasive potential." (PMID 36199046, 2022). "Indeed, CA125 (MUC16) is currently a well-established serum tumour marker for ovarian epithelial cancer and may diagnose early stage cancer." (PMID 34204432, 2021). "Moreover, MUC16-MSLN interaction can also trigger tumor invasion through MMP-7 activation." (PMID 32612258, 2020). "However, the regulation of MUC16 expression by inflammatory cytokines may differ between HPMCs and tumor cells." (PMID 31039761, 2019). "Previous studies have shown that both tumor and surrounding mesothelial cells may express MUC16." (PMID 31039761, 2019).
tumor (continued). "However, the MUC16 mutation expressed by the patient’s tumor cells does not seem to be presented by its HLA class II molecules as low binding capacities were predicted." (PMID 30459932, 2018). "Moreover, these gradients may also account for heterogeneity in MUC16 expression within tumor tissues." (PMID 26918940, 2016). "In addition, it was reported that proteolytic cleaved/cell surface MUC16 could interact with Siglec-9 of immune cells, which could act as an anti-adhesive agent to block tumor-immune cell interactions." (PMID 27167110, 2016). "MUC16 contains 16 SEA domains in its tandem repeat domain, which potentially, perhaps initiate some of the tumor-related signaling pathways." (PMID 40655139, 2025). "Mucin-16 (MUC16) is a glycoprotein overexpressed in more than 60% of patients with PDAC and is a tumor-specific biomarker." (PMID 40149293, 2025). "At increasing effector-to-target ratios, PBMCs from both M02 and M10, and M04, M05, M07, and M08 lysed SKOV3 tumor cells engineered to express MUC16 (SKOV3-Muc16ecto) and OVCAR3 cells that endogenously express MUC16/CA125." (PMID 41413213, 2025). "Because MSLN can bind to MUC16 on other tumor cells, it has been demonstrated that the MSLN–MUC16 relationship is crucial for tumor cell adhesion and metastasis." (PMID 40227645, 2025). "Furthermore, in the tumor microenvironment of high-risk LUAD patients, although the abundance of CTLs and pro-inflammatory immune signals increases, the functions of these immune cells may be constrained by MUC16-mediated immunosuppression." (PMID 40655139, 2025). "Mesothelin, through its interaction with MUC16, contributes to metastatic progression and immune suppression; CAR-T-cells targeting mesothelin have demonstrated potential in reducing tumor burden." (PMID 40940908, 2025). "Analysis of these samples showed downregulation of MUC16/CA125, elevated secretion of VEGF, and epithelial-to-mesenchymal transition in tumor cells." (PMID 41413213, 2025). "Mucins have garnered significant attention in tumor diagnosis and treatment, with some such as MUC1 and MUC16 being extensively utilized in the research of blood serum diagnostic markers." (PMID 38933439, 2024). "focused on the role of MUC16 (CA125) ADCs, discovering that a specific anti-MUC16 ADC (NAV-001) is significantly effective in eliminating tumor cells, highlighting MUC16’s potential as a therapeutic target." (PMID 38361923, 2024). "MUC16, PAX8, and SOX17, whose RNA quantity can distinguish ovarian serous cystadenocarcinoma (OSCA) from other tumor types." (PMID 38758220, 2024). "Mucin 16 (MUC16), a transmembrane glycoprotein, has recently been explored as an FGS target in preclinical tumor models." (PMID 39456534, 2024). "likewise, IHC staing affirmed that the protein expression patterns of LY6D, MET, MUC16, and WNT7A were increased in tumor sample compared to healthy samples." (PMID 38169540, 2024). "Mucins aid in determining the pathological biological characteristics of tumor cells, such as MUC1 (CA153) and MUC16 (CA125), which are used as biomarkers for monitoring malignant tumors." (PMID 38933439, 2024). "The interaction between MUC16 (CA125) and mesothelin is believed to facilitate tumor implantation and metastasis." (PMID 38637885, 2024). "Here, we aimed to expound the mechanism of MUC16 in NPC cell glycolysis and tumor progression and to determine the upstream mechanism, thus leading to tumor development." (PMID 39219440, 2024). "MUC16 was significantly enhanced in NPC tissues, which was correlated with the advanced tumor stage of patients." (PMID 39219440, 2024). "Comparison of the gene expression level in the group of CTC-negative and -positive peripheral blood samples confirmed a statistically significant difference for the expression of the Wilms tumor WT1, EPCAM, MUC16, MUC1, keratin KRT7, KRT18, and KRT19 genes." (PMID 38275400, 2024).
tumor (continued). "MUC16 and WFDC2 are known markers for HGSOC cells and Stereo-seq data demonstrated the expression of these two genes in the tumor compartment of the HGSOC sample." (PMID 38473208, 2024). "Like many other tumor biomarkers, the level of MUC16 expression is heterogeneous among different pancreatic PDX tumors and within the tumor cells in the same tumor." (PMID 39346763, 2024). "MUC16 overexpression reversed the repressive effect of ELF3 silencing on glycolysis and immune escape in NPC and accelerated tumor growth in vivo." (PMID 39219440, 2024). "All five tumor cases showed single nucleotide variations (SNVs) in MUC4, and four cases showed SNVs in MUC16, both of which were membrane-bound mucins." (PMID 37771441, 2023). "Our analyses revealed elevated levels of MUC7 and MUC16 in the saliva of patients with OSCC compared with controls, indicating their role in tumor progression." (PMID 37686462, 2023). "We show that ESK1 BiTE-secreting 4H11 CAR-T cells exhibited enhanced anticancer activity against cancer cells with low Muc16 expression, compared to 4H11 CAR-T cells alone, both in vitro and in mouse tumor models." (PMID 37214945, 2023). "Compared to other cell subtypes in the tumour microenvironment, the expression of MET, MUC16, and KRT7 was higher in pancreatic malignant cells." (PMID 37815881, 2023). "Cumulatively, this study demonstrates that anti-MUC16 chimeric mAb5E6 curtails MUC16-mediated EMT by targeting the FAK/p70S6K/N-cadherin signaling axis, thereby decreasing tumor progression and metastasis." (PMID 37567918, 2023). "MUC16 regulates glucose absorption in EOC cells by controlling GLUT1, increasing glycogen production and the energy available for tumor growth." (PMID 37664708, 2023). "MUC16 is strongly expressed in most OCs and known well as a tumor marker (CA125), because it is cleaved and released from peripheral blood, suggesting that MUC16 is an ideal antigenic target for CAR-T." (PMID 36826026, 2023). "Another NK cell-activating receptor, DNAM-1, also experiences downregulation due to factors in the tumor microenvironment, including CD155 and MUC16." (PMID 38187402, 2023). "To determine the MUC16 mediated HuR target genes in TNBC, we performed RNA immunoprecipitation (RIP) with HuR antibody, followed by a tumor metastasis PCR array." (PMID 36918912, 2023). "Single-cell analysis further revealed that MET, MUC16, and KRT7 were mainly expressed in cancer cells in PC tumour microenvironment." (PMID 37815881, 2023). "Preliminary studies have shown that targeting overexpressed molecules like mucin 16 (MUC16), annexin 2 (ANXA2), and also HER2 can sustain high tumor cells toxicity, and so dwindle tumor burden." (PMID 35093187, 2022). "Our data reflect the proven relationship between CA125 and tumor cell invasiveness through binding with E-cadherin and β-catenin complexes, and in the case of the downregulation of cell-surface CA125/MUC16, EMT is promoted." (PMID 36556382, 2022). "In CD-1 nude mice bearing high MUC16-expressing SW1990 xenograft, tumor uptake increased over time from (7.9 ± 1.0% IA/g) at 24 h p.i. to 11.6 ± 2.1% IA/g at 120 h p.i.." (PMID 36559316, 2022). "It represented a stronger prediction factor than tumor grade, stage or classical PDAC markers such as CEA, MUC16, MUC1, CA199, KRT19 and NSE, and also performed better than any m5C-score gene taken individually." (PMID 36060802, 2022). "One concern about MUC16 as a therapeutic/imaging target is that the cleavage and shedding of the extracellular domain of MUC16 in serum or in the peritoneal fluid of patients may reduce or inhibit the accumulation of M16Ab in the tumor and obscure the visualization of small lesions." (PMID 36559316, 2022).
tumor (continued). "The Clinical Proteomic Tumor Analysis Consortium (CPTAC) Discovery and Confirmatory dataset revealed strong upregulation of the MUC16 protein in high-grade PDAC tumors and the different stages of PDAC compared to the normal pancreas." (PMID 35628269, 2022). "Immunohistochemical expression of MUC16 in CCA has been studied to a limited extend, while novel prognostically relevant markers for this devastating tumor entity are urgently needed." (PMID 36230626, 2022). "Unlike the observation in NOD-SCID mice, the maximum intensity projection images of the CD-1 nude mice showed increased accumulation of 89Zr-M16Ab in MUC16-expressing SW1990 tumors overtime in which, the highest tumor uptake was observed at 120 h p.i.." (PMID 36559316, 2022). "Only six genes were present in both tumor initiation and tumor evolution stage: MUC4, MUC16, USP6, BCLAF1, KMT2C, and NOTCH2." (PMID 34918496, 2022). "Among these genes, we identified the tumor-related gene TP53INP2, which is a downstream gene regulated by MUC16." (PMID 34150633, 2021). "Beckman Coulter, Fujirebio Diagnostics, and Roche Diagnostics are established in the biomarker industry and produce FDA-approved standards (that are classified as antibody-defined tumor markers) for CA19-9, CEA, and CA125 (MUC16) clinical assays." (PMID 34514003, 2021). "We were able to confirm that co-expression of MUC16 and Gal3 present in over 90% of the HGSOC core studied, and that Gal3 knockdown strategies had tumor inhibitory effects." (PMID 33580170, 2021). "Among the four mutated genes (i.e., NCOR1, MUC16, MUC4, and RSPO2), NCOR1, MUC16, and MUC4 were reported to have been directly involved in modulating tumor microenvironment and thereby mediating drug resistance." (PMID 33504001, 2021). "MUC16 can control glucose uptake by regulating GLUT1 in EOC cells, thereby promoting glycogen synthesis, so that tumour cells produce more energy for proliferation." (PMID 33543559, 2021). "MUC16 is currently, being investigated in preclinical studies for imaging to aid in the removal of PDAC tumor during surgery." (PMID 34522225, 2021). "In this study, knockdown of MUC16 illuminated the relationship between MUC16 and HCC cellular functions, revealing that tumor-derived MUC16 acts as a suppressor of the anti-tumor immune response." (PMID 34150633, 2021). "It has been established that MUC16 binds to peripheral blood mononuclear cells (PBMC) and, in the case of NK cells, this binding blunts its anti-tumor response." (PMID 33922973, 2021). "The mRNA expression of CCBE1 and ADARB1 was significantly upregulated, while the expression of COL11A1 and MUC16 was significantly downregulated in LUAC samples compared with non-tumor samples." (PMID 32707902, 2020). "In PDAC, MUC16 and MSLN expression is correlated, and this co-expression was shown to promote cell mobility and tumor invasion, especially through the activation of JNK and ERK pathways, and also through the matrix metalloproteinase (MMP)-7 activity." (PMID 32517181, 2020). "Other tumor markers strongly expressed by the primary culture and individual clones were the mucins MUC1 and MUC16, particularly MUC1 according to RNA sequencing results." (PMID 32293552, 2020). "In contrast with the human samples, ADARB1 and CCBE1 were upregulated and COL11A1 and MUC16 were downregulated in FGF14 overexpressing xenograft tumors, which emphasized the tumor suppressing role of FGF14 in NSCLC." (PMID 32707902, 2020).
tumor (continued). "Other armored CARs in development include an IL-18-secreting CD19 or MUC16 CAR, which appears to modulate the tumor microenvironment of both hematologic malignancies and solid tumors and helps enhance endogenous anti-tumor T cell responses." (PMID 30915277, 2019). "The tumor-promoting function of p120ctn is regulated by MUC1, another well-known member of the MUC family, which is structurally similar to MUC16." (PMID 30795761, 2019). "MSLN has been shown to bind with established cell surface tumor marker MUC16, also known as CA125, leading to increased tumor cell proliferation and metastasis." (PMID 29738555, 2018). "The decrease in MUC16/CA125 antigen concentration in ascitic fluid was consistent with the overall reduction in ascitic fluid production and average tumor size." (PMID 30287783, 2018). "MUC16, also knows as as the antigen CA125, is a transmembrane mucin that protects tumor cells from the immune system promoting resistance to various chemotherapeutic agents." (PMID 29202842, 2017). "Other selected targets in clinical trials for CAR T cell therapy, an approach that also requires highly tumor-specific targets, include ERBB2, mucin-16 (MUC16), prominin 1 (PROM1) and the prolyl endopeptidase FAP (FAP)." (PMID 26700623, 2016). "This critical relationship between MUC16 and FAK can facilitate FAK-mediated downstream activation of Akt and ERK/MAPK for the tumor growth and metastasis." (PMID 27382435, 2016). "Further, our assessment of CSCs using ALDH activity, which is shown to be more relevant and efficient in identifying the PC tumor initiating cells compared to CD133, showed MUC16-Cter mediated enrichment of ALDH+ CSCs." (PMID 25691062, 2015). "Pro-inflammatory cytokines within the tumor microenvironment, such as IL-6 and TNF-α, may stimulate MUC16 transcription via JAK/STAT and NF-κB signaling pathways." (PMID 40422614, 2025). "In addition, they are developing a CD28 co-stimulatory bispecific (REGN5668), which binds MUC16 and CD28 to provide a secondary activation signal to T cells at the tumor site." (PMID 40643516, 2025). "MSLN expression has been shown to heighten tumor aggressiveness, albeit this impact is not exclusively attributable to its interaction with MUC16." (PMID 40227616, 2025). "The binding of MSLN to MUC16 not only enhances the adhesion ability of tumor cells but also upregulates the expression of MMP7 through the PI3K/AKT signaling pathway, thereby strengthening the invasive capacity of these tumor cells." (PMID 41400642, 2025). "MUC16 is not expressed in normal epithelial cells, but it is present in metaplasia and neoplasia, such as ovarian, breast, pancreas, and colon malignancies." (PMID 40385462, 2025). "MUC16‐expressing tumor cells are different from S100A2‐expressing tumor cells, and if MUC16 were not part of our panel, about a third of basal‐expressing tumors would be missing." (PMID 39935174, 2025). "Muc16-directed CAR-T cells engineered to express CCR2, the cognate receptor to CCL2, demonstrate better in vitro and in vivo tumor-directed trafficking and improve survival in tumor-bearing mice." (PMID 41424784, 2025). "Furthermore, the mRNA expression levels of FAM83A, LY6D, MET, MUC16, MYEOV, and WNT7A were elevated in PAAD tissues, while the protein expression patterns of LY6D, MET, MUC16, and WNT7A were higher in tumor sample." (PMID 38169540, 2024). "However, in tumor tissues formed by C666-1 cells with both ELF3-KD and MUC16-OE, an impaired antitumor response of T cells was observed." (PMID 39219440, 2024).